CCNB2 (cyclin B2)
Diseases named in the same sentence as CCNB2 in open-access papers (continued):
Sharing a sentence is not in itself a finding about the gene and the disease.
lung carcinoma (21 papers, 2014 to 2025). "In addition, compared with normal controls, the levels of serum circulating CCNB2 are higher in digestive tract cancer and lung cancer patients, and they are found to be significantly associated with tumor stage and metastasis status." (PMID 30254986, 2018). "CCNB2 was abnormally expressed in multiple types of tumors, such as lung cancer and gastric cancer, and correlated with the prognosis and clinical features of patients." (PMID 34354775, 2021). "Some studies reported that MAD2L1 and CCNB2 are highly expressed in gastric cancer, liver cancer, lung cancer, and other types of cancers; thus, they possibly serve as tumour-promoting genes, which are consistent with our immunohistochemical results." (PMID 34838000, 2021). "lncRNA16 is a promising biomarker for early diagnosis of lung cancer by promoting the G2/M transition by regulating the transcription of cyclin B2." (PMID 29100313, 2017). "CCDC106 facilitated AKT phosphorylation, leading to Cyclin A2 and Cyclin B2 upregulation, and ultimately enhanced proliferation of lung cancer cells." (PMID 28460455, 2017). "Several cancers, including bladder, breast, and lung cancers, showed aberrant expression of CCNB2." (PMID 39911278, 2025). "Notably, certain genes, such as CTLA4, MZB1, NIP7, and BUB1B in ADC, as well as GNG11 and CCNB2 in SCC, were found to be associated with tumor size, adding a crucial dimension to our understanding of lung cancer biology." (PMID 38612418, 2024). "CCNB2 is also a member of the cyclin family and may affect the proliferation, migration, and invasion of lung cancer cells by regulating the PI3K/Akt signaling pathway." (PMID 36714024, 2023). "In addition, we also found that PLK1, CDK1, CCNB1, and CCNB2 were upregulated in lung cancer, liver cancer, and cervix cancer tissues from HPA." (PMID 37007025, 2023). "Furthermore, AURKB, CCNB2, CDC20, CDCA5, CDCA8, CENPF, and KNTC1 are were highly expressed in lung cancer tissues and were associated with poor prognosis." (PMID 35598017, 2022). "A recent study suggested that miR-335-5p could regulate the cell cycle and metastasis of lung cancer by targeting CCNB2." (PMID 34298705, 2021). "Therefore, CCNB2 is of great value in determining the prognosis of lung cancer and may become a potential target for lung cancer treatment." (PMID 36714024, 2023). "The expression of CHEK1, CCNB1, CCNB2, and CDC2 was negatively correlated with the prognosis of patients with lung cancer (P < 0.01)." (PMID 36714024, 2023). "Combined with the results of this study, it can be inferred that CHEK1, CCNB1, CCNB2, and CDK1 are critical genes involved in cell cycle arrest and DNA damage repair in lung cancer." (PMID 36714024, 2023). "The microarray datasets GSE7670, GSE151102, GSE33532, GSE43458, and GSE19804 were further analyzed to determine the accuracy and reliability of the related expression of the four essential core genes (CHEK1, CCNB1, CCNB2, and CDK1) in lung cancer." (PMID 36714024, 2023). "CHEK1, CCNB1, CCNB2, and CDK1 are the critical core genes of lung cancer and are highly expressed in lung cancer." (PMID 36714024, 2023). "Kaplan–Meier plotter was used to analyze the prognosis of the core genes CHEK1, CCNB1, CCNB2, and CDK1 in patients with lung cancer." (PMID 36714024, 2023). "GEPIA online software was used to analyze the expression of CHEK1, CCNB1, CCNB2, and CDK1 in 969 lung cancer tissues (including lung adenocarcinoma and lung squamous cell carcinoma) and 685 normal lung tissues." (PMID 36714024, 2023). "In this study, 103 high-throughput datasets related to all subtypes of lung cancer (LC) and cerebral ischemic stroke (CIS) with the data of CCNB2 expression were collected." (PMID 35928585, 2022). "Further screening by establishing gene co-expression networks and preforming prognostic analysis identified CDK1, CCNB2, and CDC25A as the hub genes involved in lung cancer carcinogenesis and development." (PMID 34446056, 2021).
lung carcinoma (continued). "Overexpression of CCNB1 and CCNB2 has been observed in some human cancer samples, and CCNB1 and CCNB2 possess clinical significance in the diagnosis and prognosis of various cancers, such as lung cancer and pancreatic cancer." (PMID 31886163, 2019). "Therefore, CHEK1, CCNB1, CCNB2, and CDK1 may be helpful prognostic biomarkers for lung cancer." (PMID 36714024, 2023).
glioma (20 papers, 2018 to 2025). A benign or malignant brain and spinal cord tumor that arises from glial cells (astrocytes, oligodendrocytes, ependymal cells). "UBE2C, BIRC5, and CCNB2 were reported to be oncogenic and are associated with several cancers including glioma." (PMID 36105094, 2022). "CCNB2 induced a senescence-associated secretory phenotype (SASP) of glioma cells, and the malignant progression, such as invasion and excessive proliferation was mediated by secreting SASP cytokines, Cathepsin B and PGE2." (PMID 34512164, 2021). "In glioma, elevated levels of Cyclin B2 have been associated with glioma progression." (PMID 38971772, 2024). "Finally, although we preliminarily explored the biological process of CCNB2 in gliomas by GSEA, the detailed mechanism underlying the relationship between CCNB2 expression and LGG progression requires further study." (PMID 34908101, 2022). "Abnormal expression of CCNB2 has been observed in various cancers, including breast, nasopharyngeal, clear cell renal cell carcinoma, and low-grade glioma." (PMID 40564876, 2025). "Cyclin B2 triggered a senescence-associated secretory phenotype (SASP), increased invasion and augmented proliferation in glioma cells." (PMID 38971772, 2024). "Cyclin B2 (CCNB2) serves as a diagnostic and prognostic marker in various human tumors, including HCC, rhabdomyosarcoma, TNBC, and low-grade glioma." (PMID 38671354, 2024). "Previous reports have described oncogenes related to the pathogenesis of gliomas; however, few reports have evaluated the clinical and prognostic value of CCNB2 in LGG." (PMID 34908101, 2022). "Current studies support that glioma patients with high CCNB2 expression have a significantly worse survival prognosis than those with low CCNB2 expression." (PMID 35774141, 2022). "Genes associated with the neuronal differentiation pathway (Pcsk9, Runx1, Cebpb, Fzd4, Wnt7a, Ascl1, Fzd2, Edn3, Olig2, and Gpc2), gliomas (Shc1, Cdk4, E2f2, and Ccnd1), and cell cycle (Bub1b, Bub, Ccnb1, Ccnb2, and Cdc20) were significantly downregulated." (PMID 36147849, 2022). "The results meant that PGE2 was crucial in promoting anchorage-independent proliferation and thus malignant transformation of glioma cells, which worked through CCNB2/SASP/PGE2 axis in glioma cells." (PMID 34512164, 2021). "Here we compared the gene expression profiles of 693 glioma patients by HGG vs. LGG model, and identified a key factor CCNB2 for malignant transformation in glioma." (PMID 34512164, 2021). "After ectopic expression of CCNB2 and cultivated for 7 days, glioma cells were stained with PI and examined on a flow cytometer." (PMID 34512164, 2021). "Then we identified the key factor-CCNB2 which significantly promoted invasion and excessive proliferation of glioma through CCNB2/SASP/Cathepsin B and CCNB2/SASP/PGE2 axis." (PMID 34512164, 2021). "To depict the potential function of CCNB2 in malignant transformation and malignant phenotype maintaining of glioma, we evaluated the expression correlation and prognostic value of CCNB2 and its related genes in PPI network." (PMID 34512164, 2021). "Using inhibitor, PGE2 in CCNB2 medium was verified to enhance proliferation potential of glioma in vitro and in vivo, which worked through CCNB2/SASP/PGE2 axis in glioma cells." (PMID 34512164, 2021). "To firmly establish the senescence signatures of CCNB2-overexpressed glioma cells, we tested two chromatin markers and a metabolic marker for senescence." (PMID 34512164, 2021). "Summarily, this study demonstrated, for the first time, that CCNB2 functioned as a malignant transformation regulator and a tumor promoter of glioma." (PMID 34512164, 2021). "Scratch-wound healing and transwell assays demonstrated that secreted Cathepsin B from CCNB2-related senescent cells obviously facilitated migration and invasion of glioma cells." (PMID 34512164, 2021).
glioma (continued). "To confirm the role of key factor CCNB2 in senescence of glioma cells, we firstly detected the effect of CCNB2 on cell cycle and morphology." (PMID 34512164, 2021). "The function of fibronectin 1 (FN1), cyclin A2 (CCNA2), and cyclin B2 (CCNB2) in glioma OS has been reported." (PMID 32642801, 2020). "The results of correlation analysis of clinical variables between CCNB2 and lower grade gliomas showed that in both the mRNAseq_325 dataset and mRNAseq_693 dataset, the expression of CCNB2 was correlated with different histological grades, age, IDH mutational status, and 1p/19q codeletion status." (PMID 34908101, 2022). "In the 66 cells related to glioma, we found that the average expression of CCNB2 was higher, and further, CCNB2 expression was higher than that observed in colorectal and stomach cancer cell lines, but was lower than the expression in esophagus cancer or in B-cell ALL cells." (PMID 34908101, 2022). "To assess whether CCNB2 induced a SASP to promote the malignant transformation of glioma cells, we compared the cytokines concentration of medium from different groups by ELISA." (PMID 34512164, 2021). "Additionally, the phenotypes of senescence, such as G0/G1-phase arrest and cell swelling were authenticated in CCNB2 glioma cells." (PMID 34512164, 2021). "However, we were facing with a crucial question: how did CCNB2-related senescent cells work in malignant transformation for glioma?" (PMID 34512164, 2021). "We also analyzed this influence of CCNB2-related senescent cells on other glioma cells." (PMID 34512164, 2021). "In summary, PLK1, CCNA2, CCNB2, and AURKA were screened as candidate diagnostic marker genes of glioma, and hsa-let-7b-5p could inhibit the invasion and metastasis of glioma cells." (PMID 30995921, 2019). "High expression of CCNB2 in tumor tissues is closely related to the poor prognosis of gliomas." (PMID 30995921, 2019). "ORC6 emerged as a crucial regulator for the expression of key oncogenic genes, including Cyclin A2, Cyclin B2, and DNA topoisomerase II (TOP2A), within glioma cells." (PMID 38971772, 2024). "In light of bioinformatic studies highlighting the close association between ORC6 and key oncogenic genes, including Cyclin A2, Cyclin B2, and TOP2A in GBM, our study explored the potential role of ORC6 in regulating their expression in glioma cells." (PMID 38971772, 2024). "Here, the observed downregulation in both mRNA and protein levels of Cyclin A2 and Cyclin B2 upon silencing or knocking out ORC6, as well as the increased cyclins expression upon ORC6 overexpression in primary human glioma cells." (PMID 38971772, 2024). "The relationships between CCNB2 and the clinicopathological features of LGG were analyzed using the Chinese Glioma Genome Atlas (CGGA) database." (PMID 34908101, 2022). "In conclusion, the correlation of CCNB2/SASP/Cathepsin B & PGE2 axis and senescence mediated malignant transformation in glioma is valuable enough to warrant advanced explorations." (PMID 34512164, 2021). "Survival analysis indicated that high expression of CCNB2 significantly predicted poor prognosis for overall survival and recurrent-free survival (RFS) of glioma." (PMID 34512164, 2021). "In this study, we identified a key factor CCNB2 and CCNB2/SASP/Cathepsin B & PGE2 axis inducing cell senescence mediated malignant transformation in glioma." (PMID 34512164, 2021). "Subsequently, we evaluated the prognostic accuracy of CCNB2, CDC20 and MYBL2 by calculating the time‐dependent ROC, AUC (area under the ROC curve) for one‐, three‐ and five‐year survival in glioma patients." (PMID 32696617, 2020). "It was found that ASPM, CCNB2, HSPG2, KLHDC8A and RRM2 mRNA were differentially expressed in glioma tissues of different grades." (PMID 32667745, 2020). "In the present study, the expression levels of CCAN2, CCNB2, PLK1, and AURKA in glioma were upregulated, and hsa-let-7b-5p binding sites were found in four gene sequences." (PMID 30995921, 2019).
glioma (continued). "Furthermore, BMP2, NCF1, HSPB1, PIGT, PTX3, CCNA2, and CCNB2 exhibited increased expression, while DES displayed decreased expression in glioma tissues." (PMID 40656950, 2025). "In contrast, in P1 glioma cells overexpressing ORC6, “oeORC6-Slc1” and “oeORC6-Slc2,” there was a significant elevation observed in both mRNA and protein expression levels of Cyclin A2, Cyclin B2, and TOP2A." (PMID 38971772, 2024). "Subsequent studies unveiled a significant decrease in the mRNA and protein expression levels of Cyclin A2, Cyclin B2, and TOP2A within koORC6 P1 glioma xenograft tissues, where elevated levels of cleaved-caspase-3, cleaved-caspase-9, and cleaved-PARP-1 were detected, indicating apoptosis activation." (PMID 38971772, 2024). "In the development from Low to High-grade glioma, CCNB2 enhanced SASP cytokines production and the deterioration of tumor microenvironment, which significantly accelerated cell malignant transformation and progression of glioma." (PMID 34512164, 2021). "Besides, the positive correlation between Pontin and six E2F1 targets (AURKA, CDK1, CDK4, CCNA2, CCNB2, E2F8) assessed by GEPIA in glioma further supported the positive regulation of E2F1 targets expressions by Pontin." (PMID 33542204, 2021). "The results showed that hsa-let-7b-5p could regulate target genes, including cell cycle protein A2 (CCNA2), CCNB2, PLK1, and AURKA, and further affect the progress of glioma." (PMID 30995921, 2019).
lung adenocarcinoma (20 papers, 2013 to 2025). A carcinoma that arises from the lung and is characterized by the presence of malignant glandular epithelial cells. "NDC80, CENPL, ORC1, CENPN, CCNE1, and CCNB2 were significantly upregulated in the TCGA cohort as well as in the 18 pairs of lung adenocarcinoma patient samples, and high expression was significantly associated with poor prognosis in lung adenocarcinoma." (PMID 37123398, 2023). "Functionally, the downregulation of CCNB2 hampered the proliferation, invasiveness, and cell cycle entry of lung adenocarcinoma cells." (PMID 38166895, 2024). "CCNB2 is a vital hub-shared gene in both silicosis and COVID-19 and is a critical hub-shared gene of COVID-19 and lung adenocarcinoma." (PMID 37278873, 2023). "Subsequent knockdown experiments targeting CDK1 and CCNB2 using both adenocarcinoma cell lines and LCOs demonstrated their inhibitory effects on the proliferation of lung adenocarcinoma." (PMID 37941550, 2023). "miR-335-5p can target the downregulation of CCNB2, thereby inhibiting the occurrence and development of lung adenocarcinoma." (PMID 34838000, 2021). "CCNB2 is highly expressed in lung adenocarcinoma (LUAD) and hepatocellular carcinoma (HCC), and is correlated with poor prognosis." (PMID 34988076, 2021). "Additionally, miR-335-5p disrupts the cell cycle and increases lung adenocarcinoma metastasis by targeting CCNB2." (PMID 35354488, 2022). "In addition, CCNB2 mRNA is overexpressed in the tumor tissue of patients with lung adenocarcinoma, and its expression is closely related to the overall disease survival rate." (PMID 30995921, 2019). "Additionally, CCNB2 was also a biomarker for the diagnosis of lung adenocarcinoma." (PMID 34354775, 2021). "CCNB2 and AURKB were negatively correlated with B cells, macrophages, myeloid dendritic cells and CD4+T-cell infiltration in lung adenocarcinoma." (PMID 36909154, 2023). "The analysis of standard mean deviation (SMD) and summary receiver operating characteristic (SROC) reflecting expression status demonstrated significant up-regulation of CCNB2 in LC and CIS (Lung adenocarcinoma: SMD = 1.40, 95%CI [0.98–1.83], SROC = 0.92, 95%CI [0.89–0.94]." (PMID 35928585, 2022). "Overexpressed CDK5RAP3 and CCNB2, as well as suppressed RAGE, may be promising biomarkers in lung adenocarcinoma." (PMID 27610375, 2016). "utilized non-small cell LCOs to identify CDK1, CCNB2, and CDC25A as pivotal oncogenes in lung adenocarcinoma but not in lung squamous cell carcinoma." (PMID 37941550, 2023).
gastric cancer (19 papers, 2016 to 2023). A primary or metastatic malignant neoplasm involving the stomach. "For instance, in case of gastric cancer, the expression of CCNB2, OIP5 etc. genes were found to be altered along with MTUS1 mutation." (PMID 34125870, 2021). "For instance, it was found that CCNB2 is overexpressed in a variety of tumors, including gastric cancer, bladder cancer, prostate cancer, uterine corpus endometrial carcinoma." (PMID 33193623, 2020). "CCNB2 was overexpressed in multiple tumors, including bladder cancer, uterine corpus endometrial carcinoma, prostate cancer, and gastric cancer." (PMID 30254986, 2018). "It plays an important role in gastric cancer progression and development by regulating the expression of cyclin B1 and B2 (CCNB1, CCNB2) and c-MYC." (PMID 37667288, 2023). "ISL1 serves as a novel regulator for the expression of CCNB1, CCNB2 and C-MYC, which plays significant roles in gastric cancer progression and development." (PMID 27835911, 2016). "To understand the mechanism underlying the cell cycle arrest of gastric cancer cells induced by knocking down AURKB, we next examined the effect of AURKB on various key cell cycle regulatory molecules, including CCND1, CDC16, CDC6, CDC26, CCNB2, CCNF, p27 and E2F1, in gastric cancer cells." (PMID 31982864, 2020). "We were not able to confirm that HDAC4 regulates CDC2 or CYCLIN B2 in gastric cancer cells." (PMID 31703394, 2019).